PRMT7 (protein arginine methyltransferase 7)
Diseases named in the same sentence as PRMT7 in open-access papers (continued):
Sharing a sentence is not in itself a finding about the gene and the disease.
tumor (16 papers, 2015 to 2026). "We found that PRMT7 is expressed at low levels in GC tissues, and this low expression is associated with tumor size, differentiation degree, lymph node metastasis, and TNM stage." (PMID 37781082, 2023). "In xenograft models, PRMT7 inhibitor SGC3027 combined with chemotherapeutic drugs docetaxel (DTX) synergistically suppresses tumor growth." (PMID 41876450, 2026). "The expression of PRMT1, PRMT3, PRMT4, PRMT5, and PRMT7 was elevated in tumor samples compared to normal tissue, while PRMT2, PRMT8, and PRMT9 were decreased." (PMID 40399547, 2025). "PRMT7 can function as either a tumor suppressor or an oncogene in a context-dependent manner, primarily by methylating histone (e.g., H2A, H4) and non-histone substrates." (PMID 41428171, 2025). "In clear cell renal cell carcinoma, PRMT7 methylates β-catenin, preventing its ubiquitin-mediated degradation, which leads to c-Myc upregulation and accelerated tumor growth." (PMID 41204384, 2025). "PRMT7 was downregulated in GC tissues, and its expression correlated with tumor size, differentiation degree, lymph node metastasis, TNM stage, and invasion depth." (PMID 37781082, 2023). "Along with high levels of methylation of PRMT4, PRMT5, PRMT7, and hnRNPA1 in tumor samples, changes in gene alternative splicing were observed, such as those for PPARA, SREBF2, RAB27B, and WDPCP in BRCA, CRC, and PC samples." (PMID 33782401, 2021). "Similarly, hnRNPA1 is methylated by PRMT3, PRMT4, PRMT5, and PRMT7, with methylation affecting alternative splicing patterns relevant to tumor progression and therapy resistance." (PMID 41204384, 2025). "In addition, it was also noted that PRMT7-9 is highly expressed in a majority of tumor specimens, although a minor proportion demonstrates low levels of its expression." (PMID 38911125, 2024). "Hence, PRKCQ-AS1 inhibits tumor growth while regulating glycolysis and mitochondrial functions via IGF2BPs/PRMT7 signaling." (PMID 38092752, 2023). "Assessment of mRNA levels showed that PRMT7 were much lower in tumor samples than other PRMTs." (PMID 38092752, 2023). "IHC staining and bioinformatics analysis revealed significantly higher expression of PRMT7 and SOX9 in NSCLC tissues than in non-tumor tissues." (PMID 41428171, 2025). "To further investigate the role of PRMT7 in NSCLC progression, we established tumor xenograft models and found that PRMT7 overexpression promoted tumor growth in vivo." (PMID 41428171, 2025). "Combining PRMT7 inhibitors with ICI therapy induced a strong anti-tumor T cell immunity in TME and restrained tumor growth in vivo." (PMID 37273004, 2023). "We also found methylation changes in two complexes, which play an essential role in tumor development, namely H2AX complex II and PIDDsome, both having decreased average arginine monomethylation levels in PRMT7 KO cells." (PMID 35565298, 2022). "Many genes involved in drug resistance, tumor progression, or T-ALL pathogenesis were silenced in the PRMT7 knockout cells, suggesting that the high expression of PRMT7 is relevant for their expression." (PMID 35565298, 2022). "Other PRMTs also play immunomodulatory roles: in melanoma, the PRMT4 inhibitor EZF2302 restores sensitivity to anti-CTLA-4 therapy, while the PRMT7 inhibitor SGC3027 enhances anti-tumor T cell responses and reduces tumor burden when combined with ICB by promoting immune cell infiltration." (PMID 41204384, 2025). "PRMT7 protein expression in 30 paired fresh-frozen tumor and noncancerous tissues was detected through western blotting." (PMID 37781082, 2023). "Notably, PRMT1, PRMT2, PRMT3, and PRMT7 exhibited upregulation, while PRMT5, PRMT6, and PRMT8 displayed downregulation in tumor." (PMID 37781030, 2023). "Furthermore, tumor specimens showed relatively higher PRMT7 expression than normal tissues in TCGA LIHC." (PMID 35264579, 2022).
infection (3 papers, 2020 to 2021). The state of being infected such as from the introduction of a foreign agent such as serum, vaccine, antigenic substance or organism. "On day 12 PBM, similar infection rates among all strains were observed (wild type: 77.72%, Δlmjprmt7: 73.91%, Δlmjprmt7 [PRMT7]: 77.78%,) and the stomodeal valve was colonized in all infected flies." (PMID 33651805, 2021). "Eight days post blood meal (PBM), similar/high infection rates were obtained in females infected with all the three strains (wild type: 75.92%, Δlmjprmt7: 76.92%, Δlmjprmt7 [PRMT7]: 78.94%)." (PMID 33651805, 2021). "In MDMs infected with a wild-type strain, knockdown of PRMT5/PRMT7 and low expression of PRMT5 resulted in inefficient virus production like Vpr-deficient strain infections." (PMID 32210193, 2020). "Localization of infection was also similar, the stomodeal valve (SV) of P. duboscqi was colonized in similar frequency among all tested strains—wild type: 85.29%, Δlmjprmt7: 89.74%, Δlmjprmt7 [PRMT7]: 86.84%, respectively." (PMID 33651805, 2021). "The NF462 WT strain showed significantly higher virus titer than the NF462 ΔR strain in cells transfected with siRandom at 12 days post-infection, when the expression levels of PRMT5 and PRMT7 were similar (lanes 1 and 5)." (PMID 32210193, 2020). "Of interest, PRMT7-dependent pathology does not correlate with parasite burden but instead correlates with a sustainable recruitment of neutrophils to the site of infection during the chronic phase of the disease." (PMID 33651805, 2021). "Interestingly PRMT7 knockout zebrafish were more resistant to spring viremia of carp virus (SVCV) and grass carp reovirus (GCRV) infections and exhibited enhanced expression of critical antiviral genes." (PMID 34440512, 2021). "Interestingly, we verified that in the wild type and PRMT7-complemented strains there was no lesion formation, while in the knockout mutant there was a clear lesion formed in the ear after 7 weeks post infection." (PMID 33651805, 2021).
cardiac disease (1 paper, 2024). "Unlike male mice, young female mice rarely exhibit any symptoms of cardiac disease when Prmt7 is specifically depleted in the heart." (PMID 38486105, 2024).
hematological malignancy (1 paper, 2022). "Inhibitors directed against PRMTs type I, i.e., PRMT1, CARM1, PRMT5, and PRMT7, have been tested on hematological malignancy models and have shown a significant decrease in malignant cell proliferation and an increased apoptosis." (PMID 36358861, 2022).
neurodevelopmental disorder (1 paper, 2023). A behavioral and cognitive disorder with onset during the developmental period that involves impaired or aberrant development of intellectual, motor, or social functions. "Biallelic pathogenic PRMT7 variants have previously been associated with a syndromic neurodevelopmental disorder characterized by short stature, brachydactyly, intellectual developmental disability, and seizures." (PMID 36399134, 2023). "This study further delineates and expands the molecular, phenotypic spectrum and natural history of PRMT7-related syndrome characterized by a neurodevelopmental disorder with skeletal, growth, and endocrine abnormalities." (PMID 36399134, 2023).
neurological diseases (1 paper, 2019). "Thus, PRMT7-mediated NALCN inhibition provides a potential target for the development of therapeutic tools for neurological diseases." (PMID 31601786, 2019).
psychiatric disorder (1 paper, 2020). A disorder characterized by behavioral and/or psychological abnormalities, often accompanied by physical symptoms. "However, the physiological function of PRMT7 in the CA1 neurons and the relationship to psychiatric disorders are unclear." (PMID 32269286, 2020). "However, the physiological function of the PRMT7 protein in CA1 and its relationship to psychiatric disorders have not been investigated." (PMID 32269286, 2020).
PRMT7 also shares sentences with these, for which no sentence is quoted: microcephaly (2 papers); asthma (1); bipolar disorder (1); Borjeson-Forssman-Lehmann syndrome (1); CHOPS syndrome (1); Chung-Jansen syndrome (1); cognitive decline (1); Cohen syndrome (1); colon cancer (1); colorectal cancer (1); developmental delay (1); embryonal carcinoma (1); emphysema (1); germ cell tumor (1); HIV-1 infection (1); Infertility (1); lymph node metastases (1); multiple myeloma (1); muscular dystrophy (1); nephrosis (1); nonischemic cardiomyopathies (1); osteoporosis (1); promyelocytic leukemia (1); pulmonary hypertension (1); T-cell acute lymphoblastic leukemia (1); Wiedemann-Steiner syndrome (1).